TOP2A (DNA topoisomerase II alpha)
Diseases named in the same sentence as TOP2A in open-access papers (continued):
Sharing a sentence is not in itself a finding about the gene and the disease.
autism (4 papers, 2019 to 2024). Persistent deficits in social interaction and communication and interaction as well as a markedly restricted repertoire of activity and interest as well as repetitive patterns of behavior. "And it has been shown that the prenatal inhibition of Top2a causes postnatal autism-related behavioral defects in mice." (PMID 39574597, 2024). "One study identified TOP2A as a member of a core autism risk gene network consisting of 234 genes by analyzing whole-exome sequencing data." (PMID 36417527, 2022). "Both the Top2a-regulated and autism-associated gene sets have binding sites for polycomb repressive complex 2 (PRC2), a regulatory complex responsible for H3K27 trimethylation (H3K27me3)." (PMID 36417527, 2022). "Mutation of Top2a in zebrafish caused down-regulation of a set of genes highly enriched for genes associated with autism in humans." (PMID 36417527, 2022). "Disruption of Top2a preferentially alters the expression of many of the genes previously associated with autism in humans." (PMID 36417527, 2022). "Our results suggest that Top2a is indispensable for maintaining an upstream regulatory network that selectively controls the expression and epigenetic status of a large subset of autism risk genes." (PMID 36417527, 2022). "To elucidate the Top2-mediated mechanism of action, we performed RNA sequencing (RNA-seq) of Top2a mutant zebrafish and observed the down-regulation of a set of genes highly enriched for autism risk genes." (PMID 36417527, 2022). "We propose that, instead of functioning through global regulation of H3K27me3, Top2a may function by modulating the relative level of H3K27me3 between autism risk genes and non-autism risk genes." (PMID 36417527, 2022). "On the basis of the observed link between Top2a inhibition and autism-related behavioral deficits, we investigated whether Top2a depletion can selectively modulate the expression of autism risk genes using RNA-seq of 3 dpf can4−/− (Top2a) mutants." (PMID 36417527, 2022). "Why so many autism risk genes would be co-regulated by the Top2a/PRC2 mechanism is unclear." (PMID 36417527, 2022). "Prior studies have implicated Top2a in autism via different approaches." (PMID 36417527, 2022). "Thus, Top2a plays a crucial role in promoting the development of social behavior in zebrafish by the maintenance of a regulatory network that selectively controls the expression of a large subset of autism risk genes." (PMID 36768643, 2023). "Hence, Top2a may serve as a common regulatory factor controlling a large set of genes known to confer autism risk and, hence, may also serve as a link between genetic and environmental contributors to autism." (PMID 36417527, 2022). "Colocalization of Top2a, PRC2, and the PRC2-deposited epigenetic mark H3K27me3 is highly enriched among autism risk genes, including those found through human GWASs and those identified in zebrafish in this study." (PMID 36417527, 2022). "We observed that PRC2 selectively binds to autism risk genes, and the colocalization of PRC2 and Top2a is particularly enriched at those genes." (PMID 36417527, 2022). "In addition, RNA-Seq analyses performed on can4-deficient fish at 3 dpf show that Top2a depletion in zebrafish regulates autism risk genes, while ChIP-Seq data suggest that PRC2 and H3K27me3 mediate Top2a-dependent gene regulation." (PMID 36768643, 2023). "As described here, Top2a binds DNA throughout the genome, with no detected preference for genes associated with autism." (PMID 36417527, 2022). "This is consistent with the traditional view of Top2a’s role as a “housekeeping” gene with no known selectivity for autism risk genes, although a Top2a ChIP-seq experiment in neurons or developing brains of zebrafish will be needed to confirm this finding." (PMID 36417527, 2022). "Nevertheless, it is not known whether Top2a inhibition is a meaningful contributor to autism prevalence in humans." (PMID 36417527, 2022).
bladder urothelial carcinoma (4 papers, 2019 to 2025). "Moreover, in bladder urothelial carcinoma, the knockdown of TOP2A significantly reduced cancer cell proliferation." (PMID 40137900, 2025).
Cirrhosis (4 papers, 2019 to 2025). A chronic disorder of the liver in which liver tissue becomes scarred and is partially replaced by regenerative nodules and fibrotic tissue resulting in loss of liver function. "CDC20 and TOP2A are two hub genes that were implicated in the pathological development from cirrhosis to HCC." (PMID 34568357, 2021). "Hence, TOP2A, PRC1, and NUSAP1 have the potential to be liver biopsy-based markers for screening HCC high-risk patients with cirrhosis." (PMID 31001331, 2019).
Multiple Myeloma (4 papers, 2020 to 2024). "It has been observed that overexpression of TOP2A topoisomerase in myeloma cells is associated with resistance to proteasome inhibitors." (PMID 37048102, 2023). "TOP2A has been demonstrated to be another potential target for anti-myeloma therapy." (PMID 37048102, 2023). "In the context of multiple myeloma, the expression of the HNRNPA2B1, USP1, RRM1, SPAG5, PCNA and TOP2A genes has been studied." (PMID 37048102, 2023).
rectal cancer (4 papers, 2014 to 2025). A primary or metastatic malignant neoplasm that affects the rectum. "In summary, we identified five radiosensitivity-related genes associated with rectal cancer prognosis: TOP2A, MATR3, APOL6, JOSD1, HOXC6." (PMID 38012642, 2023). "In subsequent studies, we will perform cell function experiments, xenograft experiments in nude mice, and molecular mechanism experiments on irradiated human rectal cancer cell lines after overexpression or knockdown of TOP2A, MATR3, APOL6, JOSD1, and HOXC6." (PMID 38012642, 2023). "Topoisomerase inhibitors are potentially helpful to treat rectal cancer patients with TOP2A imbalances." (PMID 34771654, 2021). "Through the random survival forest analysis of these 1153 differential genes, we finally screened five key genes, which were the radiosensitivity up-regulated genes of rectal cancer: TOP2A, MATR3, APOL6, JOSD1 and the radiosensitivity down regulated gene of rectal cancer: HOXC6." (PMID 38012642, 2023). "Finally, we observed significant TOP2A copy number gains and increased expression in independent cohorts of rectal cancer patients." (PMID 34771654, 2021). "We found that TOP2A, APOL6, MATR3 were correlated with MSI and could be used as potential indicators of sensitivity to immunotherapy for rectal cancer." (PMID 38012642, 2023). "qRT-PCR revealed that MATR3 expression was different in rectal cancer tissues and adjacent non-cancerous tissues, while APOL6, HOXC6, JOSD1, and TOP2A expression was not different." (PMID 38012642, 2023).
brain tumor (3 papers, 2021 to 2023). "We also assessed the expression level of TOP2A in 20 types of paediatric brain tumors with UALCAN, and TOP2A expression in MB ranked first among these tumors." (PMID 35912241, 2022).
cervical squamous cell carcinoma (3 papers, 2020 to 2024). A squamous cell carcinoma arising from the cervical epithelium. "In patients with squamous cervical cancer, APOA1 overexpression can reduce the sensitivity of cervical squamous cells to carboplatin by regulating the expression of STAT1, CD81, C3, and TOP2A." (PMID 38212711, 2024). "However, cervical squamous cell carcinoma and endocervical adenocarcinoma (CESC) is one of the several cancer types (8 and 4 for TOP2A and CENPF, respectively) which showed most significant expression increase (ANOVA P < 1E-10 and fold change> 4) in tumor compared to normal tissues." (PMID 33023625, 2020).
gallbladder cancer (3 papers, 2019 to 2025). "One study found that TOP2A promotes the proliferation and migration of gallbladder cancer cells through the PI3K/Akt/mTOR pathway, suggesting that TOP2A is associated with the poor prognosis of patients." (PMID 36004205, 2022). "In gallbladder cancer, TOP2A promotes cell proliferation and metastasis through the activation of the PI3K/Akt/mTOR signaling pathway, suggesting that it could serve as a therapeutic target." (PMID 40831931, 2025).
metastatic colorectal cancer (3 papers, 2016 to 2022). "TOP2A contributes to oxaliplatin-resistant patients with metastatic colorectal cancer." (PMID 35069905, 2022).
oral cancers (3 papers, 2022 to 2024). "Firstly, we confirmed that etoposide significantly inhibited the protein expression of TOP2A in SCC-25 oral cancer cell line." (PMID 38957610, 2024). "We investigated the effect of TOP2A inhibition on cell survival, metabolism, and cancer stem cell self-renewal function in oral cancer cells." (PMID 38957610, 2024). "Etoposide treatment resulted in a significant reduction of TOP2A protein expression in oral cancer cell line." (PMID 38957610, 2024). "The aberrant expression of TOP2A can be related to poor prognosis in the lung, esophageal, breast, ovarian, and oral cancers." (PMID 37808164, 2023). "The networks of the candidate proteins and the chemotherapy drugs showed a strong relationship with DNA topoisomerase II alpha (TOP2A), a biomarker of oral cancers 43,44." (PMID 36517562, 2022). "Thus, we analyzed the effect of TOP2A inhibition on oral cancer cell metabolism by assessing mitochondrial respiration of OSCC cells using Mito Stress test." (PMID 38957610, 2024). "Thus, we tested the effects of etoposide on TOP2A protein expression in SCC-25 oral cancer cell line after 48h treatment." (PMID 38957610, 2024). "However, the role of TOP2A regulation in oral cancer progression is not fully explained." (PMID 38957610, 2024).
ovarian tumors (3 papers, 2012 to 2019). "A predominance of TOP2B in the combined TOP2A/TOP2B activity has been also described in ovarian tumors." (PMID 25406834, 2014).
prostate tumor (3 papers, 2014 to 2015). "We also provide evidence for the mechanism of time-related sensitivity of prostate tumor cells to TOP2A poisons." (PMID 26560244, 2015). "Mouse prostate tumors when exposed to suboptimal immunotherapy evolved into a drastically different phenotype, showing high expression of TOP2A and response to anti-TOP2A treatment." (PMID 26560244, 2015). "We performed supervised hierarchical clustering and principle component analysis using the top 100 differentially expressed genes from Top2a high and Top2a low primary prostate tumors." (PMID 25605014, 2015). "We next examined whether differences in Top2a expression in primary prostate tumor samples could identify distinct patient populations." (PMID 25605014, 2015). "We then validated TOP2A protein expression in clinical prostatic tumors using immunohistochemistry." (PMID 25237769, 2014).
psoriasis (3 papers, 2022 to 2024). An autoimmune condition characterized by red, well-delineated plaques with silvery scales that are usually on the extensor surfaces and scalp. "The main findings of this study indicate that the TOP2A and MELK genes are highly expressed in psoriasis, and higher expression of TOP2A and MELK is associated with a worse prognosis." (PMID 38382096, 2024). "We found that TOP2A and MELK were associated with skin neoplasms, skin diseases, psoriasis, erythema, dermatitis, and infections." (PMID 38382096, 2024). "TOP2A and MELK genes are highly expressed in psoriasis, and higher expression of TOP2A and MELK is associated with a worse prognosis." (PMID 38382096, 2024). "The expression levels of TOP2A and MELK genes are associated with psoriasis." (PMID 38382096, 2024). "TOP2A was screened for a wide range of relationships with multiple drugs, which may provide potential targets for the treatment and prognosis of psoriasis." (PMID 36499614, 2022). "In contrast to normal tissues, psoriasis tissues showed low expression of TOP2A." (PMID 36499614, 2022). "While the TOP2A gene may not have a direct association with psoriasis, it could potentially play a role in the pathogenesis of psoriasis through pathways related to the immune system and cell cycle regulation." (PMID 38382096, 2024). "CTD analysis found that TOP2A and MELK were related to skin neoplasms, skin diseases, psoriasis, erythema, dermatitis, and infections." (PMID 38382096, 2024). "It will involve enrichment analysis and pathway analysis to understand the significant roles of the TOP2A and MELK genes in psoriasis using publicly available datasets." (PMID 38382096, 2024). "We found that core genes (TOP2A, MELK) were highly expressed in psoriasis samples and lowly expressed in normal tissue samples, while DEPDC1B, CCNA2, DLGAP5, NUF2, ASPM were lowly expressed in psoriasis samples." (PMID 38382096, 2024). "The gene expression heatmap showed high expression of core genes (TOP2A, MELK) in psoriasis samples, while DEPDC1B, CCNA2, DLGAP5, NUF2, ASPM were lowly expressed in psoriasis samples." (PMID 38382096, 2024). "Cell cycle transcripts, which are elevated in both psoriasis and atopic dermatitis Trm2 compared to healthy controls, also show higher than median dispersion scores, including MKI67 (0.358), TOP2A (0.276), and CENPF (0.356)." (PMID 35958578, 2022). "TOP2A and AURKA genes also play important roles in psoriasis and may serve as molecular targets for precision therapy, providing new directions for further research into their mechanisms." (PMID 38382096, 2024). "This study holds potential clinical significance, as the expression levels of TOP2A and MELK may serve as potential biomarkers for assessing the condition and prognosis of psoriasis." (PMID 38382096, 2024). "However, the relationship between the TOP2A and MELK genes and psoriasis is currently unclear." (PMID 38382096, 2024). "Core genes (TOP2A, MELK) may play a regulatory role in psoriasis." (PMID 38382096, 2024). "However, the influence of the TOP2A and MELK genes on psoriasis remains unclear." (PMID 38382096, 2024).
retinoblastoma (3 papers, 2021 to 2025). A malignant tumor that originates in the nuclear layer of the retina. "In this study, we evaluated TOP2A and CDK1—two most differentially expressed genes within the retinoblastoma pathway that also demonstrated high predictive accuracy in machine learning-based classification— as potential biomarkers using immunohistochemistry." (PMID 41162745, 2025).
acute leukemia (2 papers, 2012 to 2021). A clonal (malignant) hematopoietic disorder with an acute onset, affecting the bone marrow and the peripheral blood. "Top2α activity is modulated by multiple phosphorylation sites and cancer cells phosphorylate Top2α at a number of sites not identified in non-malignant cells including the conserved catalytic tyrosine (Y805), which is phosphorylated in Jurkat cells and K562 acute leukemia cells." (PMID 34532656, 2021).
Alzheimer disease (2 papers, 2017 to 2020). A progressive, neurodegenerative disease characterized by loss of function and death of nerve cells in several areas of the brain leading to loss of cognitive function such as memory and language. "Interestingly, cell cycle dysregulation was recently identified in single cell RNA-seq analysis of microglia from a mouse model of Alzheimer’s disease (AD), with some of the same genes identified in our study, including Top2a, Hells, Ccne1, Spc25, Cenpe, Anln, Rsad2, and Ifitm335." (PMID 32792571, 2020).
anemia (2 papers, 2014 to 2015). A reduction in the number of red blood cells, the amount of hemoglobin, and/or the volume of packed red blood cells. "It is tempting to speculate that TOP2A depletion could account for the only side-effects of DRZ detected in current meta-analyses, i.e. low white blood count at nadir and anemia." (PMID 25406834, 2014).
cardiomyopathies (2 papers, 2018 to 2025). "Current knowledge also emphasizes the importance of developing Top2α-specific poisons as anticancer drugs to avoid the cardiomyopathies and secondary cancers caused by anthracyclines and other Top2 poisons." (PMID 30404148, 2018). "Other TOP2A/B-poisons such as the podophyllotoxin etoposide do not pose such a risk of cardiomyopathy despite sharing the same binding area in TOP2." (PMID 40425539, 2025). "In contrast, to optimize the antitumor activity, current research efforts aim at the discovery of Top2α-specific poisons, which are expected to not induce cardiomyopathies and secondary cancers, likely due to the Top2β." (PMID 30404148, 2018).
cervical intraepithelial neoplasia (2 papers, 2020 to 2021). "The over-expression of TOP2A seems to correlate with the grade of cervical intraepithelial neoplasia (CIN), but does not predict prognosis in CC." (PMID 33023625, 2020).
chronic myelocytic leukemia (2 papers, 2017 to 2020). "As expected, SA pretreatment did not affect stabilized TOP2A or TOP2B-DNA complexes in K562 cells, a chronic myeloid leukemia-derived cell line that does not express MPO." (PMID 27974636, 2017).
colitis (2 papers, 2024 to 2026). Inflammation of the colon. "A PPI network based on DEGs was constructed using STRING, and a highly interconnected cluster was identified as a potential functional molecular complex of colitis, including 8 hub genes, that is, NDC80, PBK, CEP55, RRM2, ASPM, NCAPG, TOP2A, and CDKN." (PMID 38661103, 2024).
cyst (2 papers, 2010 to 2021). A sac-like closed membranous structure that may be empty or contain fluid or amorphous material. "Immunofluorescence of TOP2A and HSPA2, the genes with high expressions in state 1 cells, showed differential expressions in germ cells of the same cyst in P0.5 ovaries." (PMID 34174788, 2021).
esophageal squamous cell carcinoma (2 papers, 2014 to 2022). Esophageal squamous cell carcinoma (ESCC) is a type of esophageal carcinoma (EC) that can affect any part of the esophagus, but is usually located in the upper or middle third. "However, to the best of our knowledge no study has been conducted using ERCC1, TYMS, TUBB3, RRM1 and TOP2A simultaneously in esophageal squamous cell carcinoma (ESCC)." (PMID 24926347, 2014).
head and neck cancer (2 papers, 2020 to 2024). A primary or metastatic malignant neoplasm affecting the head and neck. "Analysis of TCGA RNA-seq data from cBioPortal cancer genomic database showed that TOP2A mRNA expression was significantly higher in most cancer types including Head and Neck cancer." (PMID 38957610, 2024).
leiomyoma (2 papers, 2022 to 2025). A well-circumscribed benign smooth muscle neoplasm characterized by the presence of spindle cells with cigar-shaped nuclei, interlacing fascicles, and a whorled pattern. "To date, only two studies have demonstrated TOP2A overexpression in leiomyosarcomas versus leiomyomas through immunohistochemistry." (PMID 41162745, 2025). "There was a significant difference in TOP2A protein expression between leiomyosarcomas and leiomyomas across the three staining intensities (Pearson’s chi-square test P = 5.479e-16)." (PMID 41162745, 2025). "Two members of the retinoblastoma pathway, TOP2A and CDK1, were further shown as potential diagnostic biomarkers to distinguish leiomyomas from leiomyosarcomas and as prognostic tools in leiomyosarcoma patients." (PMID 41162745, 2025). "Previous array-based expression studies have shown that TOP2A and CDK1 are overexpressed in leiomyosarcomas when compared to leiomyomas." (PMID 41162745, 2025).
malignant peripheral nerve sheath tumor (2 papers, 2017 to 2021). Malignant peripheral nerve sheath tumor (MPNST) is a rare and often aggressive soft tissue sarcoma occurring in a wide range of anatomical sites. "Malignant peripheral nerve sheath tumors and synovial sarcomas were strongly correlated with TOP2A expression (67% and 65%, respectively)." (PMID 34638362, 2021).